DNMT3B (DNA methyltransferase 3 beta)
Diseases named in the same sentence as DNMT3B in open-access papers (continued):
Sharing a sentence is not in itself a finding about the gene and the disease.
tumor (continued). "Latent proteins LMP1 and LMP2A drive these effects through the upregulation of DNMT1, DNMT3A, and DNMT3B, leading to transcriptional silencing of tumor suppressors." (PMID 40557320, 2025). "5hmC, TET1, TET2, and DNMT3B were primarily expressed in the nuclei of tumor cells, while SDHB exhibited granular cytoplasmic staining." (PMID 41290745, 2025). "To further investigate the role of DNMT3B in tumor progression, we examined the expression level of DNMT3B in common CRC cell lines." (PMID 39108206, 2024). "In contrast, DNMT1 and DNMT3B were unchanged with only one ALCL tumor, T3, showing a significant increase in transcript levels." (PMID 38464090, 2024). "Our results showed that NSUN2, DNMT1, DNMT3A, DNMT3B, TRDMT, and ALYREF were related to high or low tumor risk, while NOP2 was related to the pTNM stage of tumors." (PMID 38579085, 2024). "PDAC cells with both DNMT3B overexpression and SLC7A11 silencing had significantly less tumor-sphere formation compared to cells with only DNMT3B overexpression." (PMID 38811540, 2024). "Western blot analysis of tumor tissues showed that treatment with sorafenib plus CHIR-99021 not only sufficiently inhibited DNMT3B expression but also increased Cleaved-PARP expression relative to that observed with sorafenib treatment alone in vivo." (PMID 38168140, 2024). "By functioning as a tumor suppressor that specifically targets DNMT3B, miR-29b holds promise as a potential therapeutic agent for HCC." (PMID 37705098, 2023). "We found that in ERα‐positive BC patients, high expressed DNMT3B means a higher proportion of T2—T4 tumor size (62.3 vs." (PMID 37881785, 2023). "In this manner, they have identified the role of DNMT3B-mediated transcription regulation as a significant factor contributing to tumor heterogeneity." (PMID 37705098, 2023). "This suggests that miR-29s exert their tumor-suppressive effects, at least in part, through the inhibition of DNMT3B expression." (PMID 37705098, 2023). "MiR-339 and miR-766 target DNA Methyltransferase 3 Beta (DNMT3B) to alter methylation pattern in tumour suppressor genes." (PMID 37205191, 2023). "The expression of four methylated transferases (DNMT1, DNMT2, DNMT3A and DNMT3B) in various tumor types was significantly correlated with the expression of PTPN2." (PMID 37884566, 2023). "This delivery system facilitates the downregulation of the target DNMT3B and ultimately leads to tumor suppression." (PMID 37705098, 2023). "At the same time, the expression levels of DNA methyltransferases (DNMT) (including DNMT1, DNMT3A and DNMT3B) in the normal and tumor samples from TCGA database were also determined." (PMID 37838802, 2023). "This miRNA acts as a tumor suppressor gene by targeting DNMT3B, Bcl-2, PI3KR1, and AKT2, which radiosensitize the tumor by regulating DNA damage." (PMID 37958993, 2023). "In this manner, miR-129-2-3p acts as a tumor suppressor in EC cells by targeting and inhibiting DNMT3B." (PMID 37705098, 2023). "Considering that CHD4 expression was positively correlated with aggressive tumour behaviour, we further focused on DNMT3B and EZH2." (PMID 36681835, 2023). "The reciprocal regulation of ncRNAs and DNMT3B can act in synergy to influence the destiny of tumor cells." (PMID 37705098, 2023). "Our results demonstrate that de novo DNA methylation mediated by DNMT3B is regulated by NO, and DBIC protects against tumor formation by preventing aberrant S-nitrosylation of DNMT3B." (PMID 36739439, 2023). "Next, we determined the effect of EGCG on DNA methylation and DNMT1, DNMT3a, and DNMT3b expression in tumor tissues." (PMID 36979768, 2023).
tumor (continued). "Nonetheless, we found 46 genes that carried either genomic or transcriptional alterations in all three resistant tumor groups, including 8 genes (Parp3, Gstm1, Il18, Padi4, Dnmt3b, Psrc1, Rif1, and Ankrd26) involved in DDR." (PMID 37209095, 2023). "NSUN2, NSUN5, NSUN6, DNMT3A, DNMT3B, ALYREF, and TET3 acted as tumor risk factors, and overexpression of these genes led to a poorer prognosis for ccRCC patients." (PMID 36661693, 2022). "According to TCGA-BRCA data, the expression of the positive genes of risk score (HJURP, IFI27, RAD51AP1, EZH2, DNMT3B, SLC7A5, DBF4 and USP18) in tumors was higher than that in normal and tumor-adjacent tissues." (PMID 36341435, 2022). "In this study, we analyzed each DNMT and DNMT3B isoforms expression by qPCR in 63 OC samples and their association with disease-free survival (DFS), overall survival (OS), and tumor progression." (PMID 36361550, 2022). "We used real-time reverse transcription PCR assays to quantify the expression of DNMT3B isoforms in 63 epithelial EOC tumor samples." (PMID 36361550, 2022). "Among several DNMTs, DNMT3B was abundantly expressed in tumor tissues and directly bound to miR-149." (PMID 35129056, 2022). "Immunohistochemistry confirmed the high expression of WTAP, DNMT1, and DNMT3B in tumor tissue, but the low expression of TRMT6." (PMID 36203569, 2022). "Firstly, we began by comparing the expression of the DNMT1, DNMT3A, and DNMT3B methyltransferases in relation to MELK tumor expression, revealing that all three were up-regulated in the context of higher MELK expression." (PMID 35511171, 2022). "Up-expression of DNMT3B was positively correlation with poor prognosis and aggressive tumor behavior." (PMID 33522955, 2021). "Others reported oncogenic functions for Dnmt3b in MYC-induced T-cell acute lymphoblastic leukemia (T-ALL) likely due to its role in tumor maintenance." (PMID 33450231, 2021). "In several studies, it has been shown that there is a significant relation between aberrant expression of tumor suppressors and increased expression of DNMT3B gene." (PMID 34914337, 2021). "Recently, we demonstrated the overexpression of DNMT1, DNMT3A, and DNMT3B in RMS tumour biopsies compared to normal skeletal muscle and the oncogenic role, which is played by DNMT3B in RMS." (PMID 34831178, 2021). "Our group also reported DNMT3A and DNMT3B overexpression in RMS tumour primary biopsies and cell lines compared to normal skeletal muscle, so revealing the oncogenic role of DNMT3B in ERMS cell lines." (PMID 34831178, 2021). "In vivo tumorigenicity assays suggested that down-regulated DNMT3B significantly inhibited tumor growth induced by Huh7-FOXC1 cells, whereas upregulation of DNMT3B salvaged the suppression tumor growth induced by FOXC1 knockdown." (PMID 33522955, 2021). "Following tumor excision, immunohistochemical analysis showed decreased DNMT3B and increased CDKN2B expression in tumors overexpressing miR-29b." (PMID 33601338, 2021). "In the current study, we identified TCF3 as a direct target of EZH2 and DNMT3B, which acts as a tumor suppressor in EC." (PMID 34175897, 2021). "The expression of DNMT3B in tumor tissues was positively correlated with the methylation of MYH11 promoter and conversely correlated with the expression of MYH11." (PMID 34380460, 2021). "Because TCL development observed in Dnmt3b+/− mice was suppressed in Dnmt3bCI/CI, we were unable to analyze molecular effects of Dnmt3b’s CA on the tumor methylome." (PMID 33450231, 2021). "The expression level of TYMS was negatively correlated with microsatellite instability (MSI) and Tumor mutation burden (TMB), and positively correlated with methylase expression in DNMT1, DNMT2, DNMT3A and DNMT3B." (PMID 35003215, 2021). "The expression of DNMT3B was detected by RT-qPCR in the collected tumor tissues and adjacent tissues, and we found that its expression was significantly elevated in the tumor tissues." (PMID 34380460, 2021).
tumor (continued). "It has been shown that Bach1 can form a complex with MAFG and the DNA methyltransferase DNMT3B, which resulted in the repression of tumor suppressor genes." (PMID 34949193, 2021). "Recently, we demonstrated the overexpression of both DNA methyltransferase 3A (DNMT3A) and 3B (DNMT3B) in RMS tumour biopsies and cell lines compared to normal skeletal muscle." (PMID 34831178, 2021). "As a DNA methyltransferase, DNMT3B has been involved in tumor progression by modulating the methylation of gene promoters important for proliferation, migration, and invasion." (PMID 33221743, 2020). "Decitabine is known to degrade DNMT1, DNMT3A, and DNMT3B proteins in tumor tissue by inducing lysosomal degradation of DNMTs." (PMID 32714333, 2020). "Another study verified that the ectopic expression of DNMT3B can promote the development of gastrointestinal cancers via the de novo methylation and transcriptional silencing of the tumor suppressor genes in mice." (PMID 32373530, 2020). "The potential therapeutic target DNMT3B complex is significantly up-regulated in tumor tissue and BAL EVs." (PMID 33233545, 2020). "DNMT3B (Cytosine-5-methyltransferase 3β) complex proteins were also up-regulated in sEVs and tumor tissue." (PMID 33233545, 2020). "For the tumor suppressors, there are 3 up-regulated genes (mutations: POLE; CNAs: DNMT3B, RECQL4) and 2 down-regulated genes (CNAs: SDHA; fusions: ZFHX3)." (PMID 32934781, 2020). "We identified a potential therapeutic target DNMT3B complex which was significantly expressed in bronchoalveolar lavage extracellular vesicles as well as in tumor tissue." (PMID 33233545, 2020). "DNMT3B is not only differentially expressed in tumor tissues, but also has significant correlation with ADHFE1 and ALDH1A2 expression." (PMID 32238162, 2020). "DNMT1 and DNMT3b cooperate for tumor suppressor silencing, and we observed a higher expression of these two proteins in K562 cells, as compared to PTPRG-expressing LAMA-84." (PMID 32225105, 2020). "DNA methylation, mediated by the combined action of three DNMTs (Dnmt1, Dnmt3a and Dnmt3b), has a particularly prominent role in tumor initiation, progression and specific tumor cell subsets." (PMID 31492191, 2019). "PGE2 administration induced the expression and activity of DNMT3B in a panel of GC cells, which in turn mediates the aberrant DNA promoter hypermethylation of tumor suppressor genes." (PMID 31534549, 2019). "We examined the expression levels of 3 DNMTs, namely Dnmt1, Dnmt3a, and Dnmt3b, that are key enzymes regulating DNA methylation in specific genes, including tumor suppressor genes." (PMID 30940675, 2019). "Tumor grafts in the MDSCs-induced MM group expressed higher levels of proliferation-related proteins, CSCs core genes and DNMT3B than the control group, but these effects were significantly reversed by antagomir-823." (PMID 30979371, 2019). "The p-STAT3 activation increases the DNMT3b/OCT4 which confers the tumor early recurrence and poor prognosis of HCC patients." (PMID 31771617, 2019). "Overexpression of DNMT3B often correlates with the epigenetic inactivation of tumor suppressor genes leading to tumor formation, including oral tumor." (PMID 31796082, 2019). "Based on the analysis the DNA methylation disorders resulted from DNMT3B, different DNA methylation probes were obtained in high and low DNMT3B expression samples and then compared to the difference between tumor and normal." (PMID 31828117, 2019). "We found that IL-6 levels and OCT4/DNMT3b expression were positively correlated with early tumor recurrence in HCC patients." (PMID 31771617, 2019). "This study demonstrates that activation of IL-6/STAT3 regulates OCT4 expression through DNMT3b, which is an indicator of early tumor recurrence and poor prognosis of HCC." (PMID 31771617, 2019).
tumor (continued). "Two different doses of resveratrol were tested and while DNMT3b differed in normal vs. tumor tissues of rats treated with low resveratrol, a high resveratrol dose resulted in decreased DNMT3b in tumor tissues with increased DNMT3b in the normal tissues." (PMID 30781847, 2019). "The protein expression levels of the pyroptosis-related protein GSDME and DNA methyltransferases (Dnmt1, Dnmt3a, and Dnmt3b) in tumor tissues were evaluated by western blotting to explore the mechanism of the in vivo antitumor activity of As2O3-NPs." (PMID 31637008, 2019). "In GC cells, PGE2 induced DNMT3B expression and activity, leading to increased methylated cytosine (5mC) and promoter methylation of tumor suppressive genes (MGMT and CNR1)." (PMID 31534549, 2019). "The expression level of three DNA methyltransferases including DNMT1, DNMT3a and DNMT3b increased and the expression level of Tet ten-eleven translocation protein 2 remarkably decreased in tumorous spleens." (PMID 29849932, 2018). "More interestingly, a correlation between the fold change of expression of DNMT3B and the fold change in nc886 methylation in the 34-paired normal vs. tumor tissues is observed (rs = 0.4402, p-value < 0.001)." (PMID 29394925, 2018). "DNMT3B is overexpressed in glioblastoma as a consequence of the hypomethylation of its own promoter and represents a marker for tumor staging and prognosis." (PMID 30406101, 2018). "Of the 3 DNMTs both DNMT3A and DNMT3B increase their transcript level in tumor compared to matched normal samples of this cohort, as calculated from the RNA-seq data." (PMID 29394925, 2018). "In other contexts, data support the idea that the reduced expression of a normal DNMT3B contributes to accelerate tumorigenesis acting as a haploinsufficient tumor suppressor." (PMID 30406101, 2018). "Patients that show overexpression of DNMT3A or DNMT3B (z-score ≥ 2) in the tumor sample are shown in dark green." (PMID 30468428, 2018). "Taken together, this indicates that DNMT3B function is required for MYC-driven tumor maintenance in T-ALL." (PMID 29100357, 2017). "Controversially, recent reports indicate that DNMT3B functions as tumor suppressor during tumor initiation." (PMID 29100357, 2017). "In fact, protein-protein interaction between SIRT1 and DNMT3B was observed both in 4C pre-malignant melanocytes and in 4C11- and 4C11+ tumor cells." (PMID 29383100, 2017). "We found that DNMT1 and DNMT3B to be consistently overexpressed in transgenic models, human tumor cell lines, as well as clinical specimens." (PMID 29100357, 2017). "In summary, we conclude that DNMT3B contributes to tumor maintenance of MYC-driven T-ALL cells through its effects on DNA methylation, and that loss of DNMT3B causes the reactivation of gene transcription through reversing promoter/CpG island methylation." (PMID 29100357, 2017). "Taken together, we propose a working model in which MYC, in addition to its role as a site-specific transcription factor, controls DNA methylation in a global manner through overexpression of DNMT1 and DNMT3B during tumor maintenance." (PMID 29100357, 2017). "Knock-down and pharmacologic inhibition of DNMT3B in T-ALL reduced cell proliferation associated with genome-wide changes in DNA methylation, indicating a tumor promoter function during tumor maintenance." (PMID 29100357, 2017). "In particular, DNMT3B transcripts are over-expressed in RMS tumours compared to NSM, suggesting that high levels of this enzyme are important molecular features of RMS." (PMID 27764816, 2016). "Our study reveals that DNMT3B levels are significantly up-regulated in RMS tumours and cell lines in comparison with normal skeletal muscle (NSM)." (PMID 27764816, 2016). "DNMT3B knowck-down also efficiently abolished the phosphorylation status of retinoblastoma (RB) tumour suppressor (p-RB) and induced a parallel slight reduction in E2F1 levels (0.2-fold), this confirming the cell cycle block at G1 phase." (PMID 27764816, 2016).
tumor (continued). "Taken together, these data clearly show that Dnmt3a and Dnmt3b possess tumor suppressor functions in the prevention of the vast majority of hematologic malignancies." (PMID 27563627, 2016). "Our study show for the first time a significant up-regulation of DNMT3B levels in 14 RMS tumour samples and 4 RMS cell lines in comparison to normal skeletal muscle." (PMID 27764816, 2016). "In summary, this study describes for the first time the over-expression of DNMT3B gene in RMS primary tumours and cell lines, suggesting that an aberrant transcriptional control mediated by this de novo DNMT is a key event in RMS development and progression." (PMID 27764816, 2016). "The parallel lowest expression of Dnmt3b and lowest 5-hmC level, especially in the tumor cells located at the invading front in the liver tissue, provides the first evidence of a clear link between these three epigenetic parameters." (PMID 27129173, 2016). "Several novel genes also positively correlated with TN disease, high Ki67 levels and tumor grade: DNMT3B, SUV39H1 and SUV39H2." (PMID 27863398, 2016). "Expression of DNMT3B was significantly up-regulated in all tumour samples in comparison to NSM, used as normal tissue, with an average increase of 81.2±9.4." (PMID 27764816, 2016). "Introduction of latent membrane protein 1 (LMP1), a viral oncoprotein from EBV, into a breast cancer cell line (MCF-7) activated DNMT1, DNMT3A, and DNMT3B, and induced methylation-silencing of tumor-suppressor gene CDH1." (PMID 26823082, 2016). "The knockdown of DNMT3B itself slightly suppressed the tumor growth in the absence and further reduced the tumor growth after γ-irradiation, confirming the radiosensitization effect of DNMT3B knockdown in the xenograft model." (PMID 26667181, 2015). "One important downstream target of miR-29b is the DNMT3B (DNA methyltransferase 3B), which silences tumor suppressors." (PMID 26404322, 2015). "The expression levels of both DNMTs were increased in tumor samples: median RQ value for DNMT3B was 3.81 and for DNMT1 1.38." (PMID 26112163, 2015). "First, resveratrol treatment resulted in a lag of tumor development as well as a significant DNMT3b down-regulation in tumors compared to normal mammary tissue." (PMID 26075205, 2015). "The data by cellular experiments showed DNMT3b silencing vectors significantly inhibited tumor cell proliferation in vitro." (PMID 24625449, 2014). "Our data revealed that inhibition of DNMT3b resulted in slower tumor growth, attenuated tumor invasion ability and epithelial mesenchymal transition, as determined by in vitro and in vivo experiments." (PMID 24625449, 2014). "Data obtained from cellular experiments and xenograft tumor growth experiments revealed that inhibition of DNMT3b resulted in slower tumor growth." (PMID 24625449, 2014). "Multivariate analyses showed that high level of DNMT3B expression and tumor differentiation were statistically significant independent poor prognostic factors." (PMID 24822169, 2014). "Surprisingly, the mean levels of DNMT1, DNMT3a, and DNMT3b overexpression have turned out to be quite similar among different tumor types." (PMID 24822169, 2014). "The effect of DNMT3b on tumor cell growth was determined by viable cell counting over six days and colony formation." (PMID 24625449, 2014). "Note that treatment with the MDM2 inhibitor, Nutlin-3, significantly reduces DNMT3A and DNMT3B expression and methylation of TSGs, as well as tumor growth in vivo." (PMID 25949795, 2014). "Because different variants of DNMT3B may have altered catalytic activity and were expressed in a tissue-specific manner, it was important to explore the genotype distribution of DNMT3B SNPs in different tumor types, particularly those that have produced contradictory results in previous reports." (PMID 24069326, 2013).